ZEB1 (zinc finger E-box binding homeobox 1)
Diseases named in the same sentence as ZEB1 in open-access papers (continued):
Sharing a sentence is not in itself a finding about the gene and the disease.
colorectal cancer (continued). "In colorectal cancer, m6A methylation can induce the upregulation of lncRNA RP11 to modulate Siah1-Fbxo45/Zeb1 complex to promote the dissemination of tumor cells." (PMID 34295922, 2021). "β-Catenin has been shown to bind directly to the ZEB1 promoter and activate its transcription in colorectal carcinomas, and the β-catenin/TCF4 complex induces the EMT activator ZEB1 to regulate tumor invasiveness." (PMID 33525359, 2021). "H19 facilitates the EMT by sponging MiR-138 and MiR-200a to promote ZEB1 and ZEB2 in colorectal cancer." (PMID 33193379, 2020). "Many studies have reported ZEB1 as a pivotal player in cancer progression by regulating EMT in gastric, breast, prostate, ovarian and colorectal cancers 9,24–27." (PMID 32153739, 2020). "From clinical data we extracted the worst prognosis when both, ZEB1 and SETD1B were highly expressed whereas in the low/low group nearly all colorectal cancer patients survived the first 5 years after surgery." (PMID 32094334, 2020). "To further examine the prognostic value of ZEB1/SETD1B axis in colon cancer patients, we investigated a data set of 177 patients with colorectal carcinoma (GEO DataSet: GSE17536)." (PMID 32094334, 2020). "In the colorectal cancer HCT-116 cell line, hypoxia-induced development of VM is due to an increase in the zinc finger E-box binding homeobox 1 (ZEB1) and HIF-1α as well as with high vimentin expression and loss of E-cadherin expression in EMT." (PMID 31993365, 2019). "OVOL2 was recently revealed as a transcriptional repressor of EMT through downregulating ZEB1 and TWIST in various cancer types such as in lung, breast, and colorectal cancers." (PMID 31404945, 2019). "Recent studies demonstrated that hTERT and ZEB1 form a complex, which directly regulates E-cadherin to promote EMT in colorectal cancer cells." (PMID 28291810, 2017). "Zinc finger E-box binding homeobox 1 (ZEB1) and Slug promoted VM formation in colorectal carcinoma and HCC, respectively, by inducing EMT." (PMID 27034014, 2017). "ZEB1 down-regulation decreased the expression of VE-cadherin and VEGFR-2 in colorectal carcinoma, which are characteristic of ECs." (PMID 28320399, 2017). "In the present study, we found that hTERT and ZEB1 form a complex, which directly binds to the E-cadherin promoter, and then inhibits E-cadherin expression and promots EMT in colorectal cancer cells." (PMID 26540342, 2016). "In this study, we demonstrate that D- and L-2HG are elevated in some of the colorectal cancer cells, and that the D- enantiomer is directly responsible for inducing EMT through increased expression of ZEB1, a master regulator of EMT." (PMID 27824159, 2016). "An increasing number of transcription factors, which can potentiate EMT, including Twist, ZEB1 and Snail have been identified; and recently, lncRNA H19 was characterized as a novel regulator of EMT in colorectal cancer." (PMID 27285757, 2016). "The β-catenin/TCF4 complex, a critical oncogenous complex, binds directly to the ZEB1 promoter and activates its transcription, thereby leading to EMT in colorectal cancer." (PMID 25871400, 2015). "In the absence of ZEB1, colorectal cancer cells are unable to initiate ER stress responses following stimuli from the tumor microenvironment." (PMID 40278350, 2025). "The loss of exosomal miR-200b-3p release from CAFs under hypoxic conditions potentially contributes to colorectal cancer progression by increasing the stemness potential of colorectal cancer cells via upregulation of CD133, SOX2, N-cadherin, ZEB1 and E2F3, which are direct targets of miR-200b-3p." (PMID 39928285, 2025). "F. nucleatum failed to induce EMT in colorectal cancer cells after we knocked down ZEB1 expression by lentivirus transduction." (PMID 39757156, 2025). "Therefore, it demonstrates that USP43 and ZEB1 govern the regulation of EMT, which plays a pivotal role in initiating and advancing colorectal cancer." (PMID 38613804, 2024).
colorectal cancer (continued). "Jägle and colleagues demonstrated, that ZEB1 was neither sufficient nor required for EMT in the LS174T colorectal cancer cells." (PMID 38139138, 2023). "For instance, data from Jägle and colleagues revealed that ZEB1 was neither sufficient nor required for EMT in LS174T colorectal cancer cells." (PMID 38139138, 2023). "Our findings demonstrate that bufalin can significantly inhibit colorectal cancer stemness and tumorigenesis, which is accompanied by its activity against EMT markers (Slug, ZEB1, N-Cadherin) and functional stem cell markers (CD44, CD133, LGR5, ALDH, and pluripotency factors)." (PMID 36362141, 2022). "We down-regulated the expression of DCBLD2 in colorectal cancer cells, and the mRNA and protein levels of transcription factors upstream of EMT signal, ZEB1, ZEB2 and SNAIL significantly decreased, which suppress epithelial genes and activate a mesenchymal expression program." (PMID 34095137, 2021). "KCNQ1OT1 is highly expressed in colorectal cancer (CRC), and its high expression predicts an unfavorable prognosis; functionally, KCNQ1OT1 facilitates CRC cell growth and metastasis by modulating the miR-217/ZEB1 molecular axis." (PMID 33909822, 2021). "Likewise, we documented that PrPC controls the expression of the EMT transcription factor ZEB1 in colorectal cancer cell lines and that PRNP gene expression is significantly correlated with an EMT signature in both colorectal cancer patients and cell panels." (PMID 34638517, 2021). "Previously, we have demonstrated that ASPP2 downregulation can promote invasion and migration by controlling β-catenin-dependent regulation of ZEB1, however, the role of ASPP1 in colorectal cancer (CRC) remains unclear." (PMID 32269211, 2020). "H19 may promote EMT by sponging miRNA-138 and miR-200a, and then upregulation of their downstream targets Vimentin,ZEB1 and ZEB2 in colorectal cancer." (PMID 33267897, 2020). "TTP has been shown to directly regulate EMT regulators, including ZEB1 (zinc finger E-box binding homeobox 1), SOX9 (sex-determining region Y box 9), and MACC1 (metastasis associated in colon cancer 1), all of which are known to be downregulated in colorectal carcinomas (CRC)." (PMID 32545247, 2020). "In colorectal cancer, lncRNA ZFAS1 may function as an oncogene by modulating ZEB1 to induce the expression of EMT, or combing with CDK1 and sponging with miR-590-3p to inhibit apoptosis." (PMID 28977885, 2017). "D-2HG, but not L-2HG, increased the trimethylation of histone H3 lysine 4 of the promoter region of ZEB1, a master regulator of epithelial-mesenchymal transition (EMT), and increased the expression of the ZEB1 gene to directly induce EMT in colorectal cancer cells." (PMID 27824159, 2016). "In addition, the β-catenin/ZEB1 axis is responsible for DDX3-induced invasiveness in colon cancer cells, lung tumor nodule formation in nude mice, and poor outcomes in colorectal cancer patients." (PMID 27007150, 2016). "In the absence of ZEB-1 colorectal cancer cells cannot mount endoplasmic reticulum-stress as a reaction on cellular stress situations like hypoxia or starvation." (PMID 24498091, 2014). "ZEB1 was found immunhistochemically at the front of invasion in colorectal carcinomas but not in central tumor areas supporting the importance of ZEB1 for EMT." (PMID 24498091, 2014). "ZEB1 expression was further evaluated by immunoblotting in two ovarian cancer (OV) cell lines (SKOV3 and ES2), two gastric cancer (GC) lines (SGC7901 and BGC823), two colorectal cancer (CRC) lines (SW620 and HCT15), and two gastrointestinal stromal tumor (GIST) cell lines (GIST882 and GIST430)." (PMID 40092690, 2025). "Moreover, research has demonstrated that cAMP responsive element binding protein 1 (CREB1) functions as a transcriptional activator of ZEB1, and that ZEB1, a pivotal regulator of EMT, significantly enhances the migratory capacity and EMT process in colorectal cancer cells." (PMID 40918458, 2025).
colorectal cancer (continued). "Similarly, the ability of ectopically expressed SNAIL to trigger a complete EMT was not affected in ZEB1 CRISPR/Cas9-KO LS174T colorectal cancer cells." (PMID 38139138, 2023). "ZEB1 and miR-200c form a two-way negative feedback to regulate the migration of colorectal cancer." (PMID 37465677, 2023). "However, since many other data support the role of ZEB1 in EMT, it needs to be clarified whether the results obtained on LS174T colorectal cancer cells might be cell line specific." (PMID 38139138, 2023). "For example, telomerase reverse transcriptase (TERT) stimulates EMT in colorectal cancer through inhibition of E-cadherin expression by binding to ZEB1; histone H4K20-specific methyltransferase SET8 stimulates EMT in prostate cancer by inhibiting E-cadherin transcription through binding to ZEB1." (PMID 34210327, 2021). "Moreover, the studies have also shown that CXCL/CXCR and PI3K/AKT/STAT3 signaling pathways participate in the regulation of EMT- and cancer stem cell- associated events, and up-regulate the expression of Snail, Twist, ZEB1, Oct4, Sox2, c-Myc, Nanog and KLF4 in colorectal cancers." (PMID 28350360, 2017). "However, the clinical significance of ZEB1 in colorectal cancer (CRC) has not been sufficiently investigated." (PMID 23420790, 2013). "Additionally, this research group demonstrated the importance of ZEB1 in HIF-1α induced metastasis with higher percentage of HIF-1α and ZEB1 positive staining and lower percentage of E-cadherin positive staining in patients' metastatic lymph nodes compared with primary colorectal cancer tissues." (PMID 32322559, 2020). "In association, Qin and collaborators have recently reported that hTERT promotes the colorectal cancer cells EMT independent of Wnt, through the ZEB1 pathway." (PMID 27507057, 2016).
hepatocellular carcinoma (154 papers, 2013 to 2025). A malignant tumor that arises from hepatocytes. "The promotion of hepatocellular carcinoma metastasis was also facilitated by the activation of the HIF1α/ZEB1 axis through CCL5 derived from cancer‐associated fibroblasts." (PMID 40062588, 2025). "Our study seeks to address a knowledge gap by presenting ZEB1 as a biomarker associated with elevated Drp1 levels, thereby directly influencing mitochondrial fission in hepatocellular carcinoma cell lines." (PMID 40830586, 2025). "We previously found that SE-associated lncRNA HCCL5 was activated by ZEB1, which increased the malignancy of hepatocellular carcinoma." (PMID 35311149, 2022). "In fact, ZEB1 has been implicated in the promotion of metastasis in other malignancies such as ovarian, gastric, pancreatic, and hepatocellular carcinoma." (PMID 31828042, 2019). "Aberrant expression of ZEB1 in endometrial cancers, gastric cancer and hepatocellular carcinoma has been associated with aggressive disease, poor differentiation, development of metastases and poor clinical prognosis." (PMID 23420790, 2013). "ZEB1 is reportedly degraded through the ubiquitin proteasome pathway, but the underlying molecular mechanism of this process remains largely unknown in hepatocellular carcinoma (HCC)." (PMID 33833131, 2021). "Increasing evidence suggests that ZEB1 is overexpressed in liver tumors, including hepatocellular carcinoma (HCC) and cholangiocarcinoma (CCA), and it correlates with advanced disease features and reduced overall survival." (PMID 41303618, 2025). "Namely, downregulated expression of ABCA8 induced epithelial transformation to mesenchyme via the ABCA8/ERK/ZEB1 pathway and promoted the progression of hepatocellular carcinoma." (PMID 41465541, 2025). "Targeting mitochondrial division in HCC by treatment with Mdivi-1 in combination with Sorafenib demonstrates a synergistic therapeutic effect in hepatocellular carcinoma (HCC) cell lines characterized by high ZEB1 expression." (PMID 40830586, 2025). "For instance, Zeb1 promoted the migration of hepatocellular carcinoma cells and enhanced the transendothelial migration of prostate cancer cells." (PMID 40806166, 2025). "Artesunate combines with OGA, which promotes O-GlcNAcylation of ZEB1 and thus reduces the protein stability of ZEB1, further inhibiting migration and invasion of hepatocellular carcinoma cells." (PMID 40771411, 2025). "Additional research has revealed TRIM26 to maintain the equilibrium of Zinc-finger E-box-binding homeobox 1 (ZEB1) ubiquitination, thereby regulating the advancement of hepatocellular carcinoma through its interaction with the deubiquitinating enzyme USP39." (PMID 38956921, 2024). "FGG regulates the expression of SLUG and ZEB1, and promotes the migration and invasion of hepatocellular carcinoma cells through EMT signal pathway." (PMID 38750571, 2024). "It has been widely reported that miRNAs controlling ZEB1 can reduce the proliferation and invasion of hepatoma cells to block EMT." (PMID 38584703, 2024). "For instance, the chemokine CCL5, produced by CAFs, promotes Hepatocellular carcinoma (HCC) metastasis by activating the HIF1/ZEB1 axis." (PMID 38445456, 2024). "In hepatocellular carcinoma, hsa_circ_00074854 knockdown reduces HuR protein stability and inhibits ZEB1 signaling pathway to inhibit HCC cell migration, invasion, and EMT." (PMID 38523627, 2024). "During hepatocellular carcinoma, ZEB1 has been shown to enhance the Warburg effect, facilitating tumorigenesis and metastasis by transcriptionally activating PFKM." (PMID 39684755, 2024). "Zinc finger E box-binding homeobox 1 (ZEB1) stimulates the Wnt/β-catenin signaling cascade, which is regulated by miR-708, in hepatocellular carcinoma cells, enhancing their proliferation, motility, and invasion and suppressing cell death." (PMID 39682738, 2024).
hepatocellular carcinoma (continued). "Our results are in perfect agreement with those of Dr. Gang Song's team, who elegantly demonstrated that USP39 and the E3 ligase TRIM26 balance the level of ZEB1 ubiquitination and thereby determine hepatocellular carcinoma cell proliferation and migration." (PMID 39736693, 2024). "ZEB1 is up-regulated in osteosarcoma, cervical, and hepatocellular carcinoma cells, contributing to the malignant phenotype of tumor cells." (PMID 37827696, 2023). "Consistently, miR-142-3p was also reported to influence the epithelial-mesenchymal transition by targeting ZEB1 in hepatocellular carcinoma (HCC)." (PMID 37403081, 2023). "Our previous studies showed that the deubiquitination enzyme USP39 and the E3 ubiquitin ligase TRIM26 balance the ubiquitination level of ZEB1, thereby determining the progression of hepatocellular carcinoma." (PMID 36707504, 2023). "USP39 and E3 ligase TRIM26 balance the level of ZEB1 ubiquitination, thereby determining the progression of hepatocellular carcinoma." (PMID 36906615, 2023). "The study of Li L shows that ZEB1 is overexpressed in hepatocellular carcinoma, which promotes tumor cell migration, invasion, and metastasis through EMT." (PMID 36313708, 2022). "For instance, circ-ZEB1.33 is overexpressed in hepatocellular cancer and has close links with the survival of hepatocellular cancer patients." (PMID 36186429, 2022). "By targeting miR-150, ZFAS1 upregulates MMP14, MMP16, and zinc finger E-box-binding homeobox 1 (ZEB1) expression, consequently increasing the occurrence of lung metastasis in hepatocellular carcinomas." (PMID 35055115, 2022). "Mechanistically, TRIM26 ubiquitinates and targets ZEB1 for degradation, while USP39 deubiquitinates and stabilizes ZEB1 to promote hepatocellular carcinoma (HCC)." (PMID 35454770, 2022). "As a significance downstream factor in the HIF1α pathway, ZEB1 plays a critical role in EMT in hepatocellular carcinoma." (PMID 35589690, 2022). "For example, ZEB1 knockdown inhibits Hoxd9-induced migration and invasion of hepatocellular carcinoma cells." (PMID 36512117, 2022). "Mechanistically, THRSP inhibited hepatocellular carcinoma progression by inhibiting the ERK/ZEB1 pathway induced EMT process." (PMID 34093825, 2021). "circKIAA1429 accelerated hepatocellular carcinoma advancement through enhancing ZEB1 mRNA stability." (PMID 33867838, 2021). "For example, circ-ZEB1.33 was overexpressed in hepatocellular carcinoma (HCC) compared to adjacent normal tissue and normal liver." (PMID 31998941, 2021). "LncRNA HCCL5 (hepatocellular carcinoma L5) which is transcriptionally regulated by ZEB1 via a super-enhancer, is a general positive regulator of EMT genes SNAIL, SLUG, TWIST and ZEB1 in a positive feedback loop." (PMID 34071216, 2021). "For instance, lncRNA-ATB can induce epithelial-mesenchymal transition (EMT) to promote hepatocellular carcinoma (HCC) invasion by competitively binding miR-200 to upregulate ZEB1 and ZEB2." (PMID 34091587, 2021). "Studies have shown that ZEB1 is abnormally expressed in many liver diseases, including hepatocellular carcinoma." (PMID 34869576, 2021). "ARHGEF11-silenced hepatoma cells displayed a clear increase in E-cadherin and a decrease in Vimentin as well as ZEB1 compared with the control group." (PMID 33122451, 2020). "For example, circ‐ZEB1.33 is highly expressed in hepatocellular carcinoma tissues, and by sponging miR‐200a‐3p, up‐regulates CDK6 levels, leading to the promotion of hepatocellular carcinoma proliferation." (PMID 32378344, 2020). "To exclude genetic variations in Hepatoma cells as the cause of selective sensitivity to UCN-01, we analysed ZEB1- and TGFβ-induced EMT models." (PMID 31543517, 2019). "We characterised its expression in a panel of commonly used Hepatoma cell lines, and demonstrated that ZEB1-induced EMT leads to chemoresistance to conventional chemotherapeutic agents." (PMID 31543517, 2019).